CD38 (CD38 molecule)
Diseases named in the same sentence as CD38 in open-access papers (continued):
Sharing a sentence is not in itself a finding about the gene and the disease.
multiple myeloma (continued). "Immunotherapy with a monoclonal anti-CD38 antibody has improved the prognosis of relapsed/refractory multiple myeloma (RRMM)." (PMID 34503133, 2021). "In summary, by targeting myeloma cells and reducing the levels of immunosuppressive adenosine, the anti-CD38 antibody daratumumab is expected to improve the quality of remission in patients with MM." (PMID 34199285, 2021). "The reason for monitoring CD38 in particular is that it is important to observe the trend of multiple myeloma cells in the bone marrow cells." (PMID 34168229, 2021). "Despite the improvement of patient’s outcome obtained by the current use of immunomodulatory drugs, proteasome inhibitors or anti-CD38 monoclonal antibodies, multiple myeloma (MM) remains an incurable disease." (PMID 33799565, 2021). "CD38 is highly and consistently expressed on myeloma cells and, to a lesser degree, other hematological and non-hematological tissues." (PMID 34638271, 2021). "Alterations in CD38/FasL regulated apoptosis have been reported in myeloma and in NK cells of gastric cancer patients." (PMID 33727923, 2021). "CD38 expression decreased in myeloma cells just after DARA was administered and recovered approximately six months after DARA was discontinued." (PMID 34638353, 2021). "Patients with multiple myeloma that is refractory to proteasome inhibitors, immunomodulators and anti-CD38 antibodies have a very poor prognosis." (PMID 34680184, 2021). "Although targeting CD38 antibodies has been approved for treatment of multiple myeloma, the function of CD38 in solid tumor, oral squamous cell carcinoma (OSCC) etc., has not been investigated." (PMID 34211854, 2021). "Daratumumab, a CD38-targeting monoclonal antibody, has significantly improved survival rates in multiple myeloma (MM), yet patients who progress on Daratumumab have dismal clinical outcomes with an overall median of less than 10 months." (PMID 34439174, 2021). "Several clinical trials, based on the use of autologous or allogeneic NK cells, are being performed in field of multiple myeloma and some of them combine NK-cells with anti-CD38 mAbs (ClinicalTrials.gov Identifier: NCT04558931)." (PMID 34203012, 2021). "As a type II transmembrane protein, CD38 is also a promising target for the immunotherapy of multiple myeloma (MM)." (PMID 34539634, 2021). "Anti-CD38 monoclonal antibody has improved the prognosis of relapsed/refractory multiple myeloma (RRMM) but some patients still experience early relapse with a poor outcome." (PMID 34503133, 2021). "Like SLAMF7, CD38 has been identified as a target for mAb to eliminate myeloma cells in patients with relapsing multiple myeloma with the use of anti-CD38 daratumumab." (PMID 33828555, 2021). "Daratumumab is a human IgGκ monoclonal antibody that targets CD38, expressed in abundance in hematopoietic cell types, especially myeloma cells." (PMID 34141513, 2021). "Daratumumab (DARZALEX®, Janssen), fully human IgG1-kappa, was the first CD38 antibody that was recognized as an emerging therapy against myeloma in the last decade." (PMID 34093594, 2021). "It is known that CD38 is highly expressed on myeloma cells, but it is also present on MDSC (myeloid-derived suppressor cells), Treg (regulatory T cell) and regulatory B cells." (PMID 33763359, 2021). "The relative increase in CD38 expression was higher on NK-92a cells compared to myeloma cells when both populations were preincubated with ATRA or IFNα." (PMID 34203012, 2021). "Isatuximab is another anti-CD38 mAb, which has similar binding affinity to myeloma cells and activity." (PMID 33799565, 2021). "The literature reported that numbers of cicrculating total CD3+, CD4+, and CD8+ T cell significantly raised with targeting CD38 treatment in multiple myeloma patients." (PMID 34211854, 2021). "Isatuximab is another monoclonal antibody to CD38 that has shown efficacy in myeloma and is now being studied in the treatment of AL amyloidosis." (PMID 33993188, 2021).
multiple myeloma (continued). "For example, a Daratumumab (CD38 mAb approved by the FDA for the treatment of multiple myeloma) based ADC was shown to deliver DM4 specifically to CD38 overexpressing cancer cells." (PMID 34067144, 2021). "Daratumumab (Dara), a humanized IgG1 (ĸ subclass) monoclonal antibody targeting the CD38 epitope, is used for the treatment of multiple myeloma." (PMID 34987512, 2021). "The recently approved monoclonal antibody, daratumumab, which targets CD38 (a receptor highly expressed on myeloma cells), has become a favorite for later line induction regimens." (PMID 33498356, 2021). "Anti-CD38 monoclonal antibodies have changed the treatment landscape of multiple myeloma in the last years." (PMID 34572927, 2021). "We also discussed breaking discovery that clonally expanded TTE are capable of eliminating autologous CD38+ plasma cells in-vitro and such play a key role in myeloma immunity." (PMID 33708212, 2021). "Daratumumab (Dara), the first FDA-approved CD38 mAb, has clearly demonstrated its therapeutic benefit, and set the new standard for future myeloma drug approval (failed IMIDs, proteosome inhibitors and CD38 mAb)." (PMID 33879198, 2021). "CD38-directed CAR-T cells have shown strong anti-multiple myeloma (MM) effect, and its “on-target off-tumor effect” against normal hematopoietic cells has been identified." (PMID 34975912, 2021). "Both CD38-expressing multiple myeloma (MM) cell lines and primary patient-derived MM bone marrow samples were successfully depleted by CD38-directed Nb-CAR-NK92 cell therapy." (PMID 34072732, 2021). "Anti-CD38 mAbs represent a promising therapy for patients with multiple myeloma (MM) since CD38 is expressed at relatively low levels on myeloid and lymphoid cells, and at high levels in various malignant plasma cells, including MM." (PMID 35008250, 2021). "CD38 (gene name: CD38 molecule) is a glycoprotein of the B cell lineage that is overexpressed specifically in many cases of multiple myeloma (MM), a blood-borne malignancy that remains incurable to this day." (PMID 33925941, 2021). "CD38 is extensively and highly expressed on MM cells, including therapy-resistant myeloma-initiating cells." (PMID 34627333, 2021). "Some patients with multiple myeloma are receiving treatment in clinical practice in England after prior exposure to a proteasome inhibitor, an immunomodulatory agent, and an anti‐CD38 monoclonal antibody." (PMID 35844690, 2021). "Anti‐CD38 monoclonal antibodies have been approved for first‐line treatment in non‐transplantable multiple myeloma (MM) patients." (PMID 34752645, 2021). "High expression of CD38 in abnormal PC clones and recent reports on the safety and response rate of Dara have made anti‐CD38 antibody‐based therapy a promising approach in AL amyloidosis." (PMID 34845849, 2021). "In this review, we summarize the rationale for using anti-CD38 antibodies in the treatment of AL amyloidosis." (PMID 33806310, 2021). "Another anti-CD38 monoclonal antibody, isatuximab, is at an earlier stage of development as a treatment for AL amyloidosis." (PMID 33806310, 2021). "Among the novel anti-myeloma IT-based agents, anti-CD38 monoclonal antibodies (mAbs) are now becoming the new backbone of treatment for NTE patients, in association with lenalidomide and dexamethasone." (PMID 32435618, 2020). "The CD38-targeting antibody daratumumab mediates its anti-myeloma activities not only through direct effects on tumor cells, but also by its effects on T-cell immunity through depletion of CD38+ immune suppressor cells." (PMID 33321969, 2020). "Since the CD38-targeted formulation improved efficacy over the nontargeted nanoparticles, these results demonstrate their potential as a new treatment option over the current standard treatment Doxil in multiple myeloma cases that overexpress CD38." (PMID 33138841, 2020).
multiple myeloma (continued). "DARA also induces polarization and redistribution of CD38 on the myeloma cell membrane surface, resulting in the release of microvesicles expressing the CD38-antiCD38 complex." (PMID 32531894, 2020). "Daratumumab (Dara) is the first-in-class human-specific anti-CD38 mAb approved for the treatment of multiple myeloma (MM)." (PMID 31936617, 2020). "The very high and homogeneous expression of CD38 on myeloma PCs makes it an attractive target for novel therapeutic strategies." (PMID 33322499, 2020). "A phase 3 study of isatuximab, another monoclonal antibody targeting CD38, plus pomalidomide and dexamethasone versus pomalidomide and dexamethasone alone in relapsed/refractory multiple myeloma, the ICARIA-MM Phase III study, has also just been published." (PMID 32138182, 2020). "It was also found that immediately after initiation of treatment with daratumumab, the expression by myeloma cells of CD38 drops to a low level, which remains low for the duration of therapy with daratumumab." (PMID 32041300, 2020). "Despite improved outcomes in patients with multiple myeloma following the advent of proteasome inhibitors, immunomodulatory agents (IMiDs), and anti-CD38 monoclonal antibodies, the majority of patients with multiple myeloma will eventually relapse." (PMID 32992506, 2020). "Tumor cell viability was determined by the identification of the double positive CD138+/annexinV+ or CD38+/annexinV+ populations from the myeloma cell marker total subset." (PMID 32405334, 2020). "The ability of CD38-specific hcAbs to induce complement-dependent cytotoxicity (CDC) was tested with a human multiple myeloma cell line (LP-1) and two human Burkitt's lymphoma cell lines (Daudi, CA46)." (PMID 32194826, 2020). "The CD38 antibody, daratumumab, has been established as one of the most promising drugs for treatment of multiple myeloma in recent years." (PMID 32041300, 2020). "Anti-CD38 antibodies kill myeloma cells by different mechanisms of action (MoA), including classical FC-dependent immune effector mechanisms, direct and immunomodulatory effects." (PMID 32899714, 2020). "Because of its high expression in plasma cells, CD38 has emerged as a suitable target for immunotherapy of multiple myeloma." (PMID 31963337, 2020). "Myeloma cells strongly express CD38 and are often treated with daratumumab, an anti-CD38 monoclonal antibody." (PMID 32546200, 2020). "In multiple myeloma, targeting CD38 is an established therapeutic approach using the human IgG1 monoclonal antibody Daratumumab." (PMID 32225002, 2020). "The NAD+ hydrolase CD38 is expressed at high levels on the cell surface of multiple myeloma (MM) cells." (PMID 33396591, 2020). "CD38 is overexpressed by several established human tumor cell lines, including LP-1 multiple myeloma, CA-46 and Daudi Burkitt lymphoma, and NK-92 natural killer cell lymphoma." (PMID 32013131, 2020). "The Ca2+ regulatory role of CD38 seems important for mitochondrial delivery from BMSCs to myeloma cells and from astrocytes to neurons in brain tissue damaged by stroke, even though the transfer occurs via a different mechanism (TNTs vs. EVs, respectively)." (PMID 32635428, 2020). "PET imaging targeted to CXCR4 and CD38 has advanced into translational clinical trials, bringing us closer to powerful imaging options for myeloma." (PMID 33142671, 2020). "The NAD-hydrolyzing ecto-enzyme CD38 is overexpressed by multiple myeloma and other hematological malignancies." (PMID 32013131, 2020). "Myeloma cells were selected by staining for the expression of the lymphocytic surface markers, including CD38 (MM.1s) and CD138 (U266)." (PMID 32405334, 2020). "For instance, daratumumab (anti-CD38 IgGκ mAb) has been successful in treating multiple myeloma in the clinic." (PMID 32093678, 2020). "Patients with multiple myeloma, who were treated with the monoclonal antibody daratumumab targeting CD38, clinically benefitted from the antibody treatment." (PMID 33584651, 2020).
multiple myeloma (continued). "There are many small molecule antagonists of CD38 have been developed and daratumumab (human IgGκ monoclonal antibody that targets CD38) have been used clinically to treat multiple myeloma and achieved good results." (PMID 32093678, 2020). "Recent observations indicate that the JAK–STAT (Janus Kinase-Signal Transducer and Activator on Transcription) axis is involved in CD38 expression by myeloma cells." (PMID 33322499, 2020). "The CD38 antigen is expressed in several hematological malignancies, and the anti-CD38 monoclonal antibodies Daratumumab and Isatuximab have an established role in the therapy of multiple myeloma." (PMID 32225002, 2020). "Another was glycoprotein CD38, expression of which characterizes immune cells and overexpression characterizes NK/T-cell lymphomas, lymphocytic leukemias, multiple myelomas and other malignancies." (PMID 33291506, 2020). "Under physiological conditions, CD38 is expressed at low levels on immune cells, while plasma cells in both healthy individuals and patients with multiple myeloma (MM) show significantly higher CD38 expression." (PMID 32922390, 2020). "Daratumumab is a human CD38-specific IgG1 antibody available for the treatment of multiple myeloma in Colombia." (PMID 32399359, 2020). "This antibody, which targets CD38, was first developed as a therapy for multiple myeloma in which CD38 is overexpressed." (PMID 35754458, 2020). "In this study, liposomal nanoparticles targeting multiple myeloma via CD38 or CD138 receptors are prepared from pre-synthesized, purified constituents to ensure increased consistency over standard synthetic methods." (PMID 33138841, 2020). "This review discusses the history of human CD38, from its initial characterization to its targeting in antibody-mediated therapy of human myeloma." (PMID 33096610, 2020). "Anti-CD38/CD3 bispecific antibodies have not yet been clinically developed but have the potential to become curative options for multiple myeloma and other lymphoid malignancies, given the widespread expression of CD38 on malignant cells." (PMID 32225002, 2020). "CD38 has found widest application in multiple myeloma (MM), where the particularly high surface density of the molecule makes it well-suited for antibody targeting." (PMID 33322499, 2020). "The number of CD45+CD34+ HSPCs was negatively correlated with the number of CD38+CD138+ myeloma cells in the bone marrow of MM patients (r = − 0.6112, p < 0.0001)." (PMID 33239656, 2020). "Daratumumab is an approved anti-CD38 monoclonal antibody used for the treatment of multiple myeloma." (PMID 31963337, 2020). "Daratumumab (Dara), an anti‐CD38 monoclonal antibody, has an immunologic mechanism of action through targeting of CD38 expressing immune cells in patients with multiple myeloma (MM)." (PMID 31991058, 2020). "The use of the CD38 monoclonal antibody daratumumab in combination with standard myeloma chemotherapy regimens has been studied extensively in recent years." (PMID 35847725, 2020). "Implanted CD20-positive fibrosarcomas demonstrated delayed growth after IP construct delivery, while CD38-positive multiple myeloma cells became less tumorigenic after premixing with the corresponding viral construct." (PMID 33291506, 2020). "The results from this study established that CD38-targeted nanoparticles have strong potential for clinical treatment for multiple myeloma." (PMID 33138841, 2020). "Isatuximab is a monoclonal antibody targeting the transmembrane receptor and ectoenzyme CD38, a protein highly expressed on hematological malignant cells, including those in multiple myeloma (MM)." (PMID 32922390, 2020). "Recently, daratumumab has been shown to specifically stimulate NK cell activity in myeloma by selectively targeting CD38(+) NK cell populations." (PMID 33634031, 2020). "Daratumumab is a human CD38-targeted monoclonal antibody approved as monotherapy for heavily pretreated relapsed and refractory multiple myeloma." (PMID 32647799, 2020).
multiple myeloma (continued). "We further analyzed the expression of CD38 on myeloma cells from 323 MM patients enrolled in isatuximab clinical trials." (PMID 32922390, 2020). "Daratumumab is a first-in-class humanized monoclonal antibody that targets the CD38 epitope approved for multiple myeloma patients who are refractory to conventional therapy." (PMID 33343293, 2020). "Recently, a false DAT positivity has been reported after daratumumab, an anti-CD38 antibody for the treatment of multiple myeloma, since CD38 is also expressed on RBCs." (PMID 33261023, 2020). "In terms of immunophenotype, the dominant clones of most myeloma patients are similar to the most differentiated normal plasma cell subset: CD38 + CD138 + CD19−." (PMID 33343342, 2020). "Another anti-CD38 mAb, isatuximab, is currently in late stage clinical development for the treatment multiple myeloma." (PMID 33003418, 2020). "Due to its high and uniform expression on myeloma cells, CD38 is an ideal target for novel therapeutic strategies especially mAbs (daratumumab and isatuximab)." (PMID 32943087, 2020). "Though direct antibody-based targeting of CD38 is well known to produce deep and effective clinical responses in multiple myeloma, data on other lymphoid malignancies are limited." (PMID 32225002, 2020). "When treatment with daratumumab is stopped, the myeloma cells will gradually start to re-express higher levels of CD38." (PMID 32041300, 2020). "Therefore, CD38 is an appealing tumor-associated antigen for targeted therapy; and monoclonal antibodies against CD38, such as daratumumab, have shown efficacy in the clinical treatment of relapsed and refractory multiple myeloma (RRMM) and newly diagnosed MM patients." (PMID 32922390, 2020). "Immunotherapy represents a promising new avenue for the treatment of multiple myeloma (MM) patients, particularly with the availability of Monoclonal Antibodies (mAbs) as anti-CD38 Daratumumab and Isatuximab and anti-SLAM-F7 Elotuzumab." (PMID 32245149, 2020). "Daratumumab is a human immunoglobulin G1 kappa (IgG1κ) monoclonal antibody that can bind to CD38 on the surface of myeloma cells and lead to cell lysis." (PMID 35847725, 2020). "During a time span of just a few years, the CD38 antibody, daratumumab, has been established as one of the most important new drugs for the treatment of multiple myeloma, both in the relapsed/refractory setting and, more recently, as a first-line treatment." (PMID 32041300, 2020). "DARA induces the release of CD38 from myeloma cells by microvesicles and the CD38 expression on MM cells is decreased after DARA exposure due to the process called trogocytosis, where there is the transfer of CD38 of MM cells to monocytes and granulocytes." (PMID 32899714, 2020). "The development of the anti-CD38 antibody Daratumumab has redefined the treatment landscape in multiple myeloma (MM), showing impressive anti-tumoral activity in one of the most insidious hematological malignancies." (PMID 32225002, 2020). "Immunotherapy is changing the paradigm of multiple myeloma (MM) management and daratumumab is the first-in-class human monoclonal antibody targeting CD38 approved for the treatment of this malignancy." (PMID 33680948, 2020). "Therapy escalation was performed with the anti-CD38 monoclonal antibody daratumumab as off label treatment, based on the therapy of refractory myeloma and led to an improvement of her clinical status." (PMID 33414761, 2020). "Both all-trans retinoic acid (ATRA) and panobinostat have been shown to increase the expression of CD38 by myeloma cells, resulting in enhanced lysis of MM cells by daratumumab in vitro and in myeloma mouse models." (PMID 32041300, 2020). "CD38 has attracted attention as a target for therapeutic antibodies and nanobodies in MM because it is highly expressed on the cell surface of most multiple myeloma cells." (PMID 33396591, 2020).